TMPRSS2 (transmembrane serine protease 2)
Diseases named in the same sentence as TMPRSS2 in open-access papers (continued):
Sharing a sentence is not in itself a finding about the gene and the disease.
lung disease (9 papers, 2020 to 2026). "It is interesting that multiple variants linked to TMPRSS2 were associated with pulmonary function or pulmonary disease medication use." (PMID 33164753, 2020). "Mapping distal cCREs linked to TMPRSS2 allowed us to next identify non-coding sequence variation that might affect cis-regulatory activity and contribute to inter-individual differences in TMPRSS2 expression and the risk of lung disease." (PMID 33164753, 2020). "Whereas the bronchioid group is characterized by pulmonary diseases (such as TMPRSS2 and DPP4), and activated cell-surface proteins." (PMID 39346064, 2024). "In comparison with wild-type mice, Tmprss2 knockout mice avoided severe infection and thus escaped from lung diseases, highlighting the importance and conservation of TMPRSS2 function in viral entry events." (PMID 34001144, 2021). "Of the various factors regulating SARS-CoV-2 entry, TMPRSS2 is the most favorable candidate for transcriptional inhibition as TMPRSS2 is required for SARS-CoV-2 entry to host cells and its expression levels are linked with lung disease severity." (PMID 32764454, 2020). "The presence of underlying lung disease was associated with a modest, non-significant reduction in TMPRSS2 expression (mean histoscores: 180.1 vs. 194.1, p = 0.62)." (PMID 41150771, 2025). "The trans-membrane serine protease 2 (TMPRSS2) is used for S protein priming by host cell protease, as demonstrated in SARS-CoV-2-infected TMPRSS2 knock-out mice that showed no pulmonary disease and lower viral replication." (PMID 37764042, 2023).
metastatic disease (9 papers, 2010 to 2025). "In metastatic disease the prevalence of TMPRSS2:ERG gene fusions was found to be similar to that observed in organ-confined prostate cancer." (PMID 20598135, 2010). "While the TMPRSS2:ERG fusion gene is an early event of prostate tumorigenesis and associated with progression from HGPIN to adenocarcinoma, the role of this genetic alteration in more advanced and metastatic disease has also been recently investigated." (PMID 33634124, 2021). "For rearrangements of TMPRSS2 and/or ERG, previous findings showed ERG rearrangements in 30–50% of localized prostate cancers and 40–50% of metastatic diseases." (PMID 24098661, 2013). "TMPRSS2-ETS fusions, and TMPRSS2-ERG fusions specifically, were common in both BRCA2d and BRCA2i, but we did not identify a difference in the frequency of these events by BRCA2 status in either primary or metastatic tumors, as has been reported for germline BRCA2d prostate cancer." (PMID 35715489, 2022).
chronic myeloid leukemia (8 papers, 2013 to 2024). "In the field of cancer, some fusion genes are cancer driver events and can be used as biomarkers or even lead to effective treatment - for instance BCR-ABL1 in chronic myeloid leukemia (CML) or TMPRSS2-ERG in prostate cancer." (PMID 28049418, 2017). "Some cancer types, such as prostate cancer or chronic myeloid leukemia (CML), are characterized by a specific fusion gene (TMPRSS2-ERG and BCR-ABL1, respectively), whereas other cancer types do not show such clear associations." (PMID 32504042, 2020). "Fusion genes are often oncogenes, such as BCR:ABL in chronic myeloid leukaemia (CML), TMPRSS2:ERG in prostate cancer, EML4:ALK in non-small-cell lung cancer (NSCLC) and so on." (PMID 24564548, 2013).
Ewing sarcoma (8 papers, 2011 to 2024). A small round cell tumor that lacks morphologic, immunohistochemical, and electron microscopic evidence of neuroectodermal differentiation. "The androgen-responsive promotor region of the TMPRSS2 gene drives robust expression of ERG, an oncogene that is also frequently involved in chromosomal translocations in Ewing sarcoma, myeloid leukemia and cervical carcinoma." (PMID 21829708, 2011).
gastric cancer (8 papers, 2013 to 2025). A primary or metastatic malignant neoplasm involving the stomach. "We found that ACE2 and TMPRSS2 have higher expression levels in intestinal-phenotype stomach (paired adjacent normal tissues of intestinal-phenotype gastric cancer) than those of gastric-phenotype stomach (paired adjacent normal tissues of diffuse-phenotype gastric cancer)." (PMID 33521016, 2020). "First, we disrupted ACE2, TMPRSS2, and LGMN in the gastric carcinoma cell line NCC-Stk-K140, which expresses moderate levels of ACE2, low levels of TMPRSS2, and high levels of LGMN and serves as a potential model system for SARS-CoV-2 infection of the gut." (PMID 40674406, 2025).
glioblastoma (8 papers, 2011 to 2024). The most malignant astrocytic tumor (WHO grade IV). "None of the synthesized peptidomimetics were able to completely inhibit infection of authentic SARS-CoV-2 (strains 20A.EU2 and Delta) in human glioblastoma U87.ACE+ cells or in human lung epithelial A549.ACE2.TMPRSS2+ cells up to 50 μM concentrations." (PMID 37240111, 2023).
melanoma (8 papers, 2011 to 2025). A malignant, usually aggressive tumor composed of atypical, neoplastic melanocytes. "In addition, our research found that the gene mutation of TMPRSS2 cannot cause changes in its own expression, but it can lead to the differential expression of multiple genes in melanoma and uterine cancer." (PMID 34951103, 2022). "As a training set, we compiled a list of all ovarian and sarcoma fusions for which validation was attempted, and added to this list the 11 melanoma fusions, the three K-562 fusions and the TMPRSS2-ERG fusion in NCI-H660." (PMID 21625565, 2011). "Methylation of TMPRSS2 gene was observed in some cases of malignant melanoma, but not in all." (PMID 30792990, 2019).
ovarian carcinoma (8 papers, 2010 to 2025). A malignant neoplasm originating from the surface ovarian epithelium. "The association of rs11203152 with TMPRSS2 loss was nominally significant in ovarian cancer (ORovarian = 4.87; Qovarian = 0.11)." (PMID 39945744, 2025). "Next, we evaluated the genes associated with TMPRSS2 in several types of cancer, that is, lung, breast, colorectal and ovarian cancer by using the R2 platform." (PMID 34951103, 2022). "Unfortunately, there is little known on the prognostic value and molecular mechanism of TMPRSS2 in ovarian cancer." (PMID 34951103, 2022). "FBLN1, a calcium-binding, acidic glycoprotein of extracellular matrix, is positively correlated with ovarian cancer progression; and elevated expression of KLK3 and TMPRSS2 have been associated with PCa aggressiveness." (PMID 21134280, 2010). "In our analysis, we found that higher OS and DFS were indicated in the low TMPRSS2 expression group of ovarian cancer relative to the elevated expression group, based on DUKE‐OC, GSE9891 and GSE26712 dataset, but the specific mechanism needs further verification and discussion in the future." (PMID 34951103, 2022). "In addition, the Kaplan–Meier plot indicated that reduced expression of TMPRSS2 has been linked with poor RFS prognosis in liver hepatocellular carcinoma, ovarian cancer, pheochromocytoma, stomach adenocarcinoma, paraganglioma, testicular germ cell tumour and uterine corpus endometrial carcinoma." (PMID 34951103, 2022).
type 2 diabetes (8 papers, 2020 to 2025). "It has also been found that patients with type 2 diabetes may be at a higher risk of SARS-CoV-2 mortality owing to epigenetic changes in the rs13015258-C allele of TMPRSS2." (PMID 35193695, 2022). "High glucose and inflammation upregulate ACE2, SGLT1 and TMPRSS2 in Caco-2/TC7 cells, potentially increasing the risk of type 2 diabetes and SARS-CoV-2 infection in humans." (PMID 40227199, 2025). "This is consistent with previous findings of increased lung levels of ACE2 and TMPRSS2 in diabetic mice, and with reports linking insulin resistance and Type 2 diabetes to severe COVID outcomes." (PMID 34684358, 2021). "It has been described that TMPRSS2 expression is increased by androgenic hormones, cigarette smoking, type 2 diabetes, H1N1 influenza virus, vanadium pentoxide, or benzo[a]pyrene diol epoxide." (PMID 34204890, 2021). "To test the hypothesis that high glucose induces inflammation in the gut and increases the risk of type 2 diabetes and SARS-CoV-2 viral entry, we first looked at the influence of glucose alone on the expression of ACE, ACE2, SGLT1, GLUT2 and TMPRSS2." (PMID 40227199, 2025). "In this study, microarray and RNA-sequencing (RNA-seq) expression data were utilized to profile the expression pattern of ACE2, ADAM17, and TMPRSS2 in type 2 diabetic (T2D) and non-diabetic human pancreatic islets." (PMID 32784802, 2020).
colorectal adenocarcinoma (7 papers, 2021 to 2025). The most common type of colorectal carcinoma. "The colorectal adenocarcinoma cell line Caco-2, frequently used as a coronavirus cell culture model with known ACE2 and TMPRSS2 expression served as a positive control." (PMID 39666439, 2025). "In contrast, the Caco2 colorectal adenocarcinoma cell line, used in several infection studies of SARS-CoV and SARS-CoV-2, has 0.47-fold lower and 56-fold higher mRNA for ACE2 and TMPRSS2, respectively, compared to wtHEK293 cells." (PMID 34200372, 2021). "This colorectal adenocarcinoma cell line was selected for the screen because the intestinal epithelium is a target for SARS-CoV-2, and these cells endogenously express ACE2 and TMPRSS2, rendering them permissive to SARS-CoV-2 infection." (PMID 40504864, 2025). "This colorectal adenocarcinoma cell line was selected for the screen because the intestinal epithelium is a target for SARS-CoV-226,27 and these cells endogenously express ACE2 and TMPRSS2, rendering them permissive to SARS-CoV-2 infection." (PMID 39026801, 2024). "Cytotoxicity of the samples was tested using several cell lines, including HDF, human breast adenocarcinoma (T47D), African green monkey kidney (Vero E6), human large intestine adenocarcinoma (HCT-8), and human lung epithelial cell lines overexpressing ACE2 and TMPRSS2 (A549ACE2/TMPRSS2)." (PMID 35622577, 2022).
Down syndrome (7 papers, 2018 to 2024). "Thus, overexpression of TMPRSS2 in Down syndrome could potentially enhance susceptibility to SARS-CoV-2 infection." (PMID 38540156, 2024). "Particularly relevant to SARS-CoV-2 infection is the genetic evidence that TMPRSS2 is triplicated in Down syndrome." (PMID 38540156, 2024). "The TMPRSS2 gene is located on chromosome 21 and was reported to show 60% higher levels of expression in Down syndrome and, thus, might contribute to the vulnerability of individuals with Down syndrome to severe COVID-19 disease." (PMID 37208193, 2023). "The transmembrane serine protease 2 (TMPRSS2)‐ (602060) gene is found on chromosome 21q22.3, suggesting that it may be overexpressed in people with Down syndrome." (PMID 36245462, 2022).
glioma (7 papers, 2021 to 2024). A benign or malignant brain and spinal cord tumor that arises from glial cells (astrocytes, oligodendrocytes, ependymal cells). "There were multiple, cancer type–specific hot spots of junctions located near known oncogenes such as KIT, PDGFRA, EGFR, CDK4, MDM2 (glioma), TMPRSS2, ERG (PCa), FGFR1, and CCDN1 (BrCa)." (PMID 34891161, 2021). "Known prominent events include TMPRSS2-ERG in PCa, EGFR, CDK4, and MDM2 in glioma, and CCND1 in BrCa." (PMID 34891161, 2021).
head and neck squamous cell carcinoma (7 papers, 2020 to 2024). A squamous cell carcinoma that arises from any of the following anatomic sites: lip and oral cavity, nasal cavity, paranasal sinuses, pharynx, larynx, and salivary glands. "Increased ACE 2 expression in Head and neck Squamous cell carcinoma patients and TMPRSS2 expression was significantly down regulated in Head and neck Squamous cell carcinoma patients." (PMID 36819393, 2023). "Similar to our results, the expression of TMPRSS2 gene is lower in the oral cavity of the head and neck squamous cell carcinoma, confirming that other factors such as inflammatory responses may be involved." (PMID 34749700, 2021). "In Head and neck squamous cell carcinoma (HNSCC), an aberrant upregulation of a group of specific microRNAs has been highlighted that could target TMPRSS2 at a post-transcriptional level reducing its levels in the tumor." (PMID 38255667, 2023). "Interestingly, cancer tissues, particularly in head and neck squamous cell carcinoma (HNSCC) and lung cancers, demonstrate lower ACE2 and TMPRSS2 expression, potentially rendering them more resistant to SARS-CoV-2 infection." (PMID 38420467, 2024). "However, the expression profiles of ACE2, TMPRSS2 and FURIN have not been comprehensively examined in normal oral mucosa (NOM) and OSCC, a major subgroup of head and neck squamous cell carcinoma (HNSCC)." (PMID 34726347, 2022).
liver cancer (7 papers, 2020 to 2024). An epithelial or non-epithelial malignant neoplasm that arises from the liver. "There is, thus, a possibility that TMPRSS2 is also associated with liver cancer." (PMID 37610679, 2023). "The high expression of the ACE2 and TMPRSS2 proteins was observed in HepG2 (liver cancer) and 293T (human embryonic kidney) cells, which were utilized as screening models to investigate the entry of SARS-CoV-2 into host cells." (PMID 38892254, 2024). "We studied ACE2 and TMPRSS2 in transcriptomic datasets totaling 1503 liver cancers, followed by high-resolution confocal multiplex immunohistochemistry and quantitative image analysis of a 41-HCC tissue microarray." (PMID 35115564, 2022). "In more detail, a significant reduction of TMPRSS2 and CLEC4M in kidney and liver cancers, as well as a significant increase of DPP4 in thyroid cancer, was highlighted." (PMID 32970391, 2020). "As liver cancer cells are in vitro models for the study of SARS-CoV-2 entry and cytopathic effects, we extensively studied mRNA, protein expression and localization of the viral receptors ACE2 and TMPRSS2 in human HCCs." (PMID 35115564, 2022). "Therefore, the purpose of this study was to analyze ACE2 and TMPRSS2 expression and localization in human liver cancers and in non-tumor livers." (PMID 35115564, 2022).
metastatic prostate carcinoma (7 papers, 2008 to 2022). A carcinoma that arises from the prostate gland and has spread to other anatomic sites. "Consequently, the overexpression of target gene TMPRSS2 plays an important role in promoting the progression of metastatic prostate cancer." (PMID 35164166, 2022). "Some of them have been described as predictors of therapy response or ways of helping to guide therapies such as TMPRSS2-ERG fusion, PTEN status, presence of AR-V7 splice variant, mutations in DNA-repair genes such as BRCA2/1, etc. in metastatic prostate cancer patients." (PMID 35207452, 2022). "If replicated, the results presented here may provide insight into the mechanism by which the TMPRSS2-ERG gene fusion arises and also contribute to diagnostic evaluations for determining the subset of men who will go on to develop metastatic prostate cancer." (PMID 18694509, 2008). "One of the androgen pathways in COVID-19 infection is the transmembrane protease, serine 2 (TMPRSS2) gene that is expressed mainly in the adult prostate, and in metastatic prostate cancers; it is also found in tissues like lung, kidney, pancreas, colon, small intestine, and liver." (PMID 34484179, 2021).
pancreatic cancer (7 papers, 2019 to 2022). "Top expressing tissues were similar on gene and protein levels for ACE2 (colorectal, kidney, pancreas, and stomach), TMPRSS2 (prostate and pancreatic cancers), and CTSL (renal and skin cancers)." (PMID 33633121, 2021). "AKT1 with TMPRSS2 and FURIN were positively correlated in all contexts except for pancreatic cancer and healthy pancreas, respectively." (PMID 33796097, 2021).
pulmonary fibrosis (7 papers, 2020 to 2023). Chronic progressive interstitial lung disorder characterized by the replacement of the lung tissue by connective tissue, leading to progressive dyspnea, respiratory failure, or right heart failure. "ACE2 and TMPRSS2 were also expressed in FSP-1+ lung fibroblasts in bleomycin-induced pulmonary fibrosis, and when combined with PM exposure, they were further upregulated." (PMID 33706759, 2021). "We therefore developed KC knockout mice (KC−/−, KC-deficient) and treated them with bleomycin plus PM to explore the role of KC and the expression of ACE2 and TMPRSS2 in pulmonary fibrosis." (PMID 33706759, 2021). "Since type II alveolar epithelial cells express both ACE2 and TMPRSS2 in normal individuals, it is also believed that their derived fibroblasts express these two molecules in bleomycin-induced pulmonary fibrosis mice and IPF patients." (PMID 33706759, 2021). "The severity of pulmonary fibrosis and the expression of ACE2 and TMPRSS2 caused by PM exposure were blocked by deletion of KC, a murine homologue of IL-8, or treatment with reparixin, an inhibitor of IL-8 receptors CXCR1/2." (PMID 33706759, 2021). "TMPRSS2 also plays a vital role in the immuno-pathology of coronavirus infections including SARS-CoV-2 across lungs by inducing lung fibrosis." (PMID 33072093, 2020). "ACE2 and TMPRSS2 were both highly expressed in areas of pulmonary fibrosis." (PMID 33706759, 2021). "Quantitative data revealed that KC depletion significantly reduced pulmonary fibrosis and the expression of ACE2 and TMPRSS2." (PMID 33706759, 2021). "In the absence of a human model, we established a mouse model of bleomycin-induced lung fibrosis combined with administration of PM to investigate the effects of pulmonary fibrosis and air pollution exposure on the expression of ACE2 and TMPRSS2." (PMID 33706759, 2021). "Quantitative data further showed that treatment with reparixin significantly improved pulmonary fibrosis and suppressed the levels of ACE2 and TMPRSS2 in mice receiving bleomycin plus PM." (PMID 33706759, 2021). "Together, these data suggested that exposure to PM increased the severity of bleomycin-induced pulmonary fibrosis and upregulated the levels of ACE2 and TMPRSS2." (PMID 33706759, 2021). "We have shown that ACE2 and TMPRSS2 were expressed at the same time by part of FSP-1 positive fibroblasts in human lung fibrotic tissues and in an animal lung fibrosis model." (PMID 33706759, 2021). "In addition, based on our findings, PM induced deterioration of pulmonary fibrosis in a bleomycin animal model and increased the expression of ACE2 and TMPRSS2." (PMID 33706759, 2021). "In the current study, we hypothesized that air pollution exposure and pulmonary fibrosis may increase the expression of ACE2 and TMPRSS2 in the lung alveolar region." (PMID 33706759, 2021). "Since type II alveolar epithelial cells express both of ACE2 and TMPRSS2 in normal lung tissues, these FSP-1 + ACE2 + TMPRSS2+ in pulmonary fibrosis lung tissues may derive from transformed type II alveolar epithelial cells." (PMID 33706759, 2021). "However, in our results, ACE2 and TMPRSS2 are expressed in the alveolar region and partially co-localize in certain FSP-1 positive lung fibroblasts, and show enhanced expression after the development of pulmonary fibrosis." (PMID 33706759, 2021). "However, in our results, ACE2 and TMPRSS2 were expressed in lung alveolar region and co-localized with FSP-1 positive fibroblasts in part, and exhibited enhanced expression after the development of lung fibrosis." (PMID 33706759, 2021).